RN7SKP61 (RN7SK pseudogene 61)
Gene: Miscellaneous RNA gene on chromosome 3 (78,161,698 to 78,161,992, forward strand). Ensembl gene ENSG00000222574.
Homologues: Orthologues: chimpanzee 7SK (99% identical), zebrafish rn7sk (72% identical). Paralogues in human: 7SK (74% identical), RN7SKP160 (73% identical), RN7SKP118 (71% identical), RN7SKP187 (70% identical), RN7SKP48 (70% identical), RN7SKP174 (69% identical), RN7SKP62 (68% identical), RN7SKP81 (68% identical), RN7SKP227 (67% identical), RN7SKP185 (67% identical), RN7SKP292 (67% identical), RN7SKP76 (66% identical), and 284 more.